DRD3 (dopamine receptor D3)
Diseases named in the same sentence as DRD3 in open-access papers (continued):
Sharing a sentence is not in itself a finding about the gene and the disease.
sleep disorder (1 paper, 2024). A change from the patient's baseline sleeping pattern, in the hours slept and/or an alteration/dysfunction in the stages of sleep. "We mapped the dopamine receptor family DRD1, DRD3, and other targets for improving sleep disorders with the components of AMS to the dopaminergic metabolic signaling pathway and constructed a metabolic pathway map." (PMID 38784223, 2024).
type 2 diabetes (1 paper, 2018). "Through this approach, we identified DRD3 and CACNA1E to be potential targets for the treatment of type 2 diabetes." (PMID 30131871, 2018).
psychiatric disorder (10 papers, 2015 to 2024). A disorder characterized by behavioral and/or psychological abnormalities, often accompanied by physical symptoms. "Polymorphisms in the DRD3 gene have been studied in various psychiatric disorders." (PMID 26131011, 2015). "In comparison to these well-established associations, the connection of psychiatric disorders and behavioral traits with other DR genes are much less consistent, although there are some GWA studies showing that DRD1 is associated with educational attainment and DRD3 with neuroticism." (PMID 39619336, 2024).
cancer (8 papers, 2019 to 2023). A tumor composed of atypical neoplastic, often pleomorphic cells that invade other tissues. "Our preliminary review of data in cBioportal (cbioportal.org) indicated that a portion of neuroendocrine prostate (16.7%), cervical (4.5%), ovarian (>4%), and head and neck (>3%) cancers have amplifications of DRD3." (PMID 33945569, 2021). "Previous evidence has shown that dopamine may affect cancer development through other dopamine receptors, different from DRD3, by acting directly on tumour cells or indirectly on cells associated with the tumour microenvironment." (PMID 36428964, 2022). "Therefore, the therapeutic potential of targeting DRD3 in cancer should be experimentally evaluated in future studies." (PMID 36428964, 2022). "Thus, it is possible that DRD3 antagonism could provide a therapeutic option for other tumor types if amplification or aberrant cell signaling in multiple cancers results in DRD3 expression." (PMID 33945569, 2021). "Changes in DRD3 levels along with GDNF, GNAL, HRH2, CAV2, and DLG4 were characteristic of G1 cancer." (PMID 34768458, 2021). "Very few studies to date have investigated the expression of DRD3 in cancer, much less defined DRD3 function or effects of inhibition in GBM or other cancers." (PMID 33945569, 2021). "However, there are little research related to the effect of DRD3 in HCC cancer progression, while numerous studies about the carcinogenesis of DRD1 and DRD2 have been published, and tumor-related research on DRD3 is rare." (PMID 36456906, 2022). "The expression levels of DRD3 in the control groups of all cancer and normal cell lines were not considerably different and were almost the same." (PMID 34952904, 2021).
neurological diseases (8 papers, 2016 to 2024). "DRD2 and DRD3 belong to the D2-like receptors and are normally associated with neurological diseases." (PMID 32867127, 2020). "In addition, our findings further support the repurposing of drugs designed to target brain signaling pathways; DRD3 antagonists have been primarily developed for other neurological disorders such as addiction." (PMID 33945569, 2021). "Moreover, the study identified DRD3 and SEPSECS as critical players in seizures, shedding light on their possible roles in neurological disorders." (PMID 39635461, 2024).
tumor (8 papers, 2019 to 2025). "Thus, the association between DRD3 expression and CS progression observed in this study may be a result of the down-regulation of anti–tumor cell cytokines." (PMID 31850367, 2019). "The suppressive activity of Treg, which is detrimental to anti-tumour immunity, is also inhibited by DRD3 signalling." (PMID 36428964, 2022). "Only the role of DRD3-signalling in DCs has been addressed in the context of the anti-tumour response." (PMID 36428964, 2022). "Here, we have addressed the role of DRD3-signalling on the leading actor of anti-tumour response, the CD8+ T-cells." (PMID 36428964, 2022). "The results show that mice receiving Drd3-sufficient or Drd3-deficient OT-I transgenic CD8+ T-cells displayed a significant reduction in tumour growth over time, compared with those mice that did not receive OT-I transgenic CD8+ T-cells." (PMID 36428964, 2022). "Based on the outcome, knock-down of DRD3 could promote tumor growth in vivo, and SCH772984 could also abolished this effect in vivo." (PMID 36456906, 2022). "Moreover, DRD3 stimulation has been proposed to increase the M1 inflammatory profile in macrophages, a subset that contributes to the anti-tumour response." (PMID 36428964, 2022). "Thus, it is likely that DRD3 signalling on CD4+ T-cells also potentiates the anti-tumour immune response." (PMID 36428964, 2022). "Nevertheless, although the effect of DRD3 stimulation in T-cells and macrophages is expected to reinforce the anti-tumour immune response, DRD3 signalling on DCs and NK cells is probably harmful to anti-tumour immunity." (PMID 36428964, 2022). "Furthermore, mice receiving Drd3−/− OT-I transgenic CD8+ T-cells showed faster tumour growth, compared with those receiving Drd3+/+ OT-I transgenic CD8+ T-cells." (PMID 36428964, 2022). "Notably, most of the relevant actors involved in the anti-tumour immune response have been described to express DRD3, including CD8+ T-cells, effector CD4+ T-cells, Treg, macrophages, NK cells, B-cells, and DCs." (PMID 36428964, 2022). "Whether improved survival could also be observed when tumor bearing mice were treated with other DRD antagonists that have efficacy against DRD3 should also be explored." (PMID 33945569, 2021). "In the case of DRD3, little is known about its involvement in tumor biology." (PMID 34768458, 2021). "DAXX and DISC1 have been associated with tumor invasion in previous studies; to our knowledge, DRD3 has not." (PMID 31850367, 2019). "DA influences tumor behavior via its receptors, categorized as D1-like (DRD1, DRD5) and D2-like (DRD2, DRD3, DRD4), which vary in tumor expression and function." (PMID 40456735, 2025). "Based on the results of univariate analysis of all clinicopathological characteristics, HBsAg status, Child–Pugh classification, tumor size, satellite nodule status, TNM classification and DRD3 expression were included in the multivariate Cox regression model." (PMID 36456906, 2022). "According to those findings, we theorised that the impaired expansion observed in mice harbouring Drd3-deficient CD8+ T-cells could be due, at least in part, to a reduced migration of these cells through the secondary lymphoid organs, where APC would present the tumour antigens." (PMID 36428964, 2022). "In this regard, it has been shown that DRD3-signalling on DCs reduces the antigen cross-presentation to CD8+ T-cells, dampening the anti-tumour response." (PMID 36428964, 2022). "Here, we studied the role of dopamine receptor D3 (DRD3), which displays the highest affinity for dopamine, in the function of CD8+ T-cells and its consequences in the anti-tumour immune response." (PMID 36428964, 2022).
tumor (continued). "For instance, our previous study indicated that DRD3 signalling in DCs reduces the presentation of tumour-derived antigens to CD8+ T-cells, thereby reducing the priming of tumour-specific lymphocytes and attenuating the anti-tumour immune response." (PMID 36428964, 2022). "DRD3 mRNA expression was significantly higher in nontumor tissues than in tumor tissues, and the same result had been shown in the cohort of GSE14520." (PMID 36456906, 2022). "The DRD2 inverse agonist and antipsychotic haloperidol improved the efficacy of an epidermal growth factor receptor inhibitor, although haloperidol (which also has efficacy in the nanomolar range on DRD3, DRD4, and several other receptors) was insufficient to decrease tumor growth alone." (PMID 33945569, 2021). "DRD3 mRNA expression was significantly higher in nontumor tissues than in tumor tissues." (PMID 36456906, 2022). "First, DRD3 mRNA was detected in tumor and adjacent nontumor tissues." (PMID 36456906, 2022). "In the competing-risks model, tumor differentiation (P = 0.005), metastasis (P = 0.014), invasion (P = 0.028), AJCC stage (P = 0.003), Enneking stage (P = 0.036), and DAXX (P = 0.039), and DRD3 (P = 0.019) expression were independent predictors of death from CS." (PMID 31850367, 2019). "Both DRD2 and DRD4 have significantly higher expression in the non-tumor samples than the GBM samples, while DRD3 has similar expression between GBM and non-tumor." (PMID 33945569, 2021).
movement disorder (3 papers, 2012 to 2021). Neurological conditions resulting in abnormal voluntary or involuntary movement, which may impact the speed, fluency, quality and ease of movement. "In a population with chronic mental illness, various SNPs in 10 candidate genes (PPP1R1B, BDNF, DRD3, DRD2, HTR2A, HTR2C, COMT, MnSOD, CYP1A2, and RGS2) reached nominally significant (p≤0.05) associations with drug-induced movement disorder." (PMID 22615781, 2012). "In a population with chronic mental illness, various tag SNPs in 7 candidate genes (GRIN2B, GRIN2A, HSPG2, DRD3, DRD4, HTR2C, and NQO1) reached nominally significant (p≤0.05) associations with drug-induced movement disorders." (PMID 23226551, 2012).
inflammation (1 paper, 2025). Aberrant reaction of the microcirculation characterized by movement of fluid and leukocytes from the blood into extravascular tissues. "In a previous study conducted in mouse models of gut inflammation, we showed that the selective stimulation of Drd3 in Treg attenuates their suppressive activity and limits their recruitment into the colonic mucosa." (PMID 41155360, 2025).
DRD3 also shares sentences with these, for which no sentence is quoted: Parkinsonism (4 papers); metabolic syndrome (2); neurodegenerative disease (2); rest tremor (2); agranulocytosis (1); anxiety disorder (1); autism spectrum disorder (1); behavioral addictions (1); bipolar II disorder (1); central nervous system disorder (1); cocaine use disorder (1); cognition disorders (1); Cushing syndrome (1); developmental delay (1); Familial adenomatous polyposis (1); fibrosis (1); Huntington disease (1); Hypertension (1); inflammatory bowel disease (1); lung squamous cell carcinoma (1); narcolepsy (1); ocular hypertension (1); Osteochondroma (1); post-traumatic stress disorder (1); Primrose syndrome (1); prostate (1); psychostimulant addiction (1); restless leg syndrome (1); rheumatoid arthritis (1); Seizure (1).
A further 3 diseases each share a sentence with DRD3 in 1 paper.